BCL2 (BCL2 apoptosis regulator)
Diseases named in the same sentence as BCL2 in open-access papers (continued):
Sharing a sentence is not in itself a finding about the gene and the disease.
ovarian carcinoma (continued). "Interestingly, we have recently reported increased levels of urinary Bcl-2 in ovarian cancer patients suggesting that reduced epithelial Bcl-2 staining with tumor progression may reflect a transition from cellular expression of Bcl-2 to secreted Bcl-2 associated with disease progression." (PMID 19852858, 2009). "In agreement with previous studies we found that over 50% of ovarian cancers stained for Bcl-2, but we also detected Bcl-2 staining in normal and benign ovarian specimens." (PMID 19852858, 2009). "The data suggest alterations in Bcl-2 expression and lymphocyte infiltration correlate with epithelial ovarian cancer progression." (PMID 19852858, 2009). "Taken together, these results suggest that, in human ovarian carcinoma cells, high BCL-2 levels (either naturally occurring or through gene transfection) confers a trend towards sensitivity not resistance to platinum drugs." (PMID 10646901, 2000). "In addition, 48 h after CE action on ovarian cancer cells, Western blot analysis showed that the expression level of Bak was significantly increased, while the expression level of Bcl-2 was significantly decreased." (PMID 40071097, 2025). "Moreover, NEAT1 indirectly modulated BCL2 expression in ovarian cancer cells by sponging miR-34a-5p58." (PMID 40730640, 2025). "Resveratrol activates Caspase-3 and Caspase-8, and up-regulates the protein expression of Bax, while inhibiting anti-apoptotic proteins like Bcl-2, in order to induce apoptosis in luminal squamous cell carcinoma, cervical carcinoma, colon carcinoma, ovarian carcinoma, and uterine leiomyoma cells." (PMID 40490812, 2025). "Furthermore, overexpression of CCN1 can inhibit carboplatin-induced apoptosis by decreasing Bax expression and increasing Bcl-xL, Mcl-1, and Bcl-2 levels in ovarian cancer cells." (PMID 40234387, 2025). "In addition, it inhibited autophagy of epithelial ovarian cancer by enhancing the stability of BCL2 apoptosis regulator (BCL2), which has an antiapoptotic role." (PMID 38503745, 2024). "In addition, 6‐shogaol increases the expression of Bax, caspase‐3, and caspase‐9 in ovarian cancer cell lines but decreases Bcl‐2 levels." (PMID 39055196, 2024). "Moreover, XTP8 exerts its influence on the apoptosis of ovarian cancer cells through the BCL2/BAX pathway." (PMID 38717641, 2024). "It was also reported that miR-140 targeted BCL9 and BCL2 and prevented colorectal cancer progression, miR-148a targeted BCL2 in non-small cell lung cancer, and miR-340 decreased BCL2 and increased Bax to induce cell apoptosis in ovarian cancer." (PMID 38675388, 2024). "In ovarian cancer SK-OV-3 cells, XAP enhanced the antiproliferative and proapoptotic effects of PTX on tumor cells and inhibited PTX-induced PXR and the antiapoptotic protein Bcl-2, exerting antitumor effects and inhibiting the malignant progression of ovarian cancer." (PMID 38957318, 2024). "However, another study by Liang and Zhao showed an increased expression of the BCL2 protein in ovarian cancer tissues in the case of lymphoid metastases and post-operative recurrence tissue." (PMID 38003498, 2023). "As research shows, BCL2 expression is extremely complex in ovarian cancer cells and tissues." (PMID 38003498, 2023).
ovarian carcinoma (continued). "This may increase the intracellular cisplatin concentration; thus, inhibiting the phosphorylation of Akt, mTOR and Erk, and decreasing the level of Bcl-2, leading to ovarian cancer cells apoptosis." (PMID 37940982, 2023). "For instance, in ovarian cancer, it has been proven that Bcl‐2, through Ca2+ homeostasis, attenuates cisplatin cytotoxic effects, and targeting Bcl‐2 may result in overcoming therapy resistance in ovarian cancer." (PMID 38151790, 2023). "BCL-2 is a crucial regulator of apoptosis and plays a vital role in apoptosis in ovarian cancer." (PMID 35719961, 2022). "The proliferation of ovarian cancer cells is considerably inhibited by berberine in a dose- and time-dependent way, and apoptosis is induced, probably via downregulation of anti-apoptotic genes survival and BCL-2, and pro-apoptotic gene BAX upregulation." (PMID 36144625, 2022). "It was suggested that silencing the expression of EEF1D may inactivate the PI3K/Akt signaling pathway and regulate the balance of Bax/Bcl-2 to induce apoptosis, inhibit cell viability and reduce DNA damage repair in ovarian cancer cells." (PMID 35672728, 2022). "Collectively, dezocine may induce apoptosis of ovarian cancer cells by regulating the Bcl-2/Bax axis and Caspase 3 activity." (PMID 36568517, 2022). "Additionally, CD276 also inhibits tumor growth in ovarian cancer via activating the PI3K/AKT signaling pathway through the upregulation of BCL-2, which is related to chemoresistance." (PMID 36358792, 2022). "Similarly, matrine not only reduces the expression level of Bcl-2 and increases the expression of caspase-8, but also inhibits the viability, and migration and induces apoptosis of ovarian cancer cells by up-regulating the p38MAPK and JNK pathways." (PMID 36686745, 2022). "In A2780 ovarian cancer cells, baicalein decreased Bcl-2 and activated caspase-3 and -9." (PMID 36142874, 2022). "Furthermore, interaction with the 3’-untranslated regions (3’-UTRs) stabilized BCL2, encouraging ovarian cancer growth and chemotherapy resistance." (PMID 35982949, 2022). "Overexpression of HDAC4 or increased nuclear location in ovarian cancer cell line-SKOV3 could promote the mRNA expression of BCL2 and inhibited the cell apoptosis." (PMID 33845782, 2021). "TQ (6 μg/mL) has reduced the permeability of plasma and mitochondrial membrane in the Caov-3 ovarian cancer cell line and decreased the nuclear area with a notable inhibition for both Bcl-2 and Bax, in addition to triggering the oxidative stress and increasing the apoptosis in ovarian cancer." (PMID 33923474, 2021). "It will be interested to investigate whether the FBXO16/hnRNPL axis also regulates the stability of Bcl-2 mRNA in ovarian cancer in the future." (PMID 34333526, 2021). "In addition, our results showed different expression levels of Bcl2 RNA and protein in the ovarian cancer cells, pointing to the significant controlling role played by translational and post-translation mechanisms that have been observed in lymphoid tissues." (PMID 34199287, 2021). "In addition, linc00312 participated in drug resistance as it sensitized ovarian cancer cells to cisplatin by activating the Bcl-2/Caspase-3 pathway." (PMID 34336850, 2021). "Therefore, we tested the expression levels of Bcl-2 and Bax in the ovarian cancer tissues from cisplatin-resistant/sensitive patients by Western blot assay and calculated the ratio of Bax/Bcl-2." (PMID 33585454, 2020). "Furthermore, with the exploration of the BORA silencing transcriptional landscape, we identified downstream effectors such as CDK6 and BCL2 whose inhibition can be used as targeted therapies for ovarian cancer management." (PMID 32268485, 2020). "Thus, we further studied the influence of PTFSs on the Bcl-2 family in ovarian cancer cells, including the pro-apoptotic proteins Bax and Bad, anti-apoptotic proteins Bcl-2 and Bcl-xL." (PMID 32560563, 2020).
ovarian carcinoma (continued). "The decrease in Bcl‐2/Bax ratio suggested that BPP could significantly activate apoptosis in ovarian cancer." (PMID 32519803, 2020). "Therefore, knockdown of PRSS1 expression led to an increased ratio of Bax/Bcl-2, which promoted the apoptosis of ovarian cancer cells." (PMID 33585454, 2020). "The selective induction of apoptosis in both ovarian cancer cell lines in this study might result from its effects on the expression of Bcl-2, Bax and DR5 proteins." (PMID 32235536, 2020). "A similar study reported that Paris saponin II induced apoptosis in ovarian cancer cell might also result from its effects on the expression of Bax, Bcl-2, and cytochrome c proteins." (PMID 32752095, 2020). "PAX8 silenced cells show a lower percentage of cell-survival compared to that of the parental cells indicating that the loss of PAX8 brings to an increased sensitivity to anoikis of ovarian cancer cells and accordingly decreased bcl-2 and increased Bax expression." (PMID 31832016, 2019). "However, the levels of m6A+BCL-2 mRNA were decreased in ovarian cancer A2780 cells infected with LV121-ALKBH5 as compared with that of A2780 cells infected with LV121-NC." (PMID 30987661, 2019). "However, the BCL-2 mRNA F/V ratio was increased in ovarian cancer A2780 cells infected with LV121-ALKBH5 as compared to that of A2780 cells infected with LV121-NC." (PMID 30987661, 2019). "Bcl-2 has also been identified in ovarian cancer cells to promote survival and drug resistance." (PMID 31766284, 2019). "We decreased BCL9 expression in the ovarian CaoV3 serous cancer cell line and ovarian ES-2 clear cancer cell line, which inhibited BCL2 expression and increased the BAX/BCL2 expression ratio, promoted cell apoptosis, and inhibited the proliferation of ovarian cancer cells." (PMID 31827404, 2019). "However, in the late stage of ovarian cancer, the anti-apoptotic protein of Bcl-2 was found to be over-expressed." (PMID 31089361, 2019). "Thus, Klf4 seems to regulate Bcl-2 or Bax differently in ovarian cancer cells than in normal ovarian cells due to unidentified cellular factors." (PMID 30587813, 2018). "Luteolin could enhance cisplatin induced apoptosis in cisplatin-resistant ovarian cancer CAOV3/DDP cells via decreasing Bcl-2 expression." (PMID 30454003, 2018). "Notably, this study provided new evidence that siRNA-mediated EpCAM knockdown had an effect on apoptosis by downregulating Bcl-2 expression and upregulating Bax expression in ovarian cancer cells." (PMID 28574829, 2017). "BT is known to reduce bcl-2 in ovarian cancer cell lines resulting in apoptosis." (PMID 28931042, 2017). "It was hypothesized and demonstrated that regulation of human telomerase reverse transcriptase (hTERT) and BCL-2 may serve as explanations for increases in apoptosis of ovarian cancer cells with the incorporation of combined SFN and EGCG." (PMID 28534825, 2017). "In addition, WNT2B can increase the ability of metastasis and chemoresistance of ovarian cancer through the caspase-9/BCL2/BCL-xL pathway and EMT/p-AKT pathways." (PMID 28053597, 2017). "Western blot showed that miR-519d transfection in ovarian carcinoma cells downregulated RhoC (Ras homolog gene family member C), Bcl-2, cyclin D1, survivin, MMP2, MMP9, STAT3 (signal transducer and activator of transcription 3), and HuR (ELAV-like RNA-binding protein 1) expression (P < 0.05)." (PMID 28146423, 2017). "In ovarian cancer cells, we showed that knockdown of BCL2 also reduces CSC-like populations, suggesting that the LARP1-mediated anti-CSC phenotype may also be mediated via BCL2 expression." (PMID 26717985, 2016). "This led us to question whether a Bcl-2 selective inhibitor would be of therapeutic use in a significant proportion of ovarian cancer patients." (PMID 27080533, 2016). "Interestingly, also the La-related protein 1 (LARP1) has recently been found to promote survival and cisplatin resistance by stabilizing Bcl2 mRNA in in ovarian cancer cells." (PMID 27105491, 2016).
ovarian carcinoma (continued). "However, continued efforts to prove the ability of pulchrin A targeting Bcl-2-regulated apoptosis as well as further in vivo animal studies should be conducted to provide more evidence to the anticancer effect of pulchrin A on ovarian cancer." (PMID 27136097, 2016). "Ovarian cancer patients with methylated BLU had significantly shorter progression free survival, in vitro, BLU could decrease the Bcl-2/Bax ratio in ovarian cancer cells when encountered with PTX." (PMID 26900348, 2016). "Studies have shown that Bcl-2 and Bax play important roles in mediating drug-induced apoptosis and drug resistance in various tumor cells, including hepatocellular carcinoma, bladder, lung and ovarian cancer." (PMID 27888624, 2016). "Unfortunately, Bcl-XL appears to be more frequently deregulated in ovarian cancer than Bcl-2." (PMID 27080533, 2016). "In addition, we observed the reduction of Bcl-2 expression accompanied with elevated levels of cleaved-caspase-9 and cleaved-caspase-3 in ovarian cancer cells treated with PMBPs." (PMID 26539720, 2015). "The importance of BCL-2 to regulation of apoptosis and the complex interplay with autophagy has been recognized previously 16,24, and a therapeutic role in this context has been identified in ovarian cancer." (PMID 25487826, 2015). "Baekelandt and coworkers demonstrated 39% positivity of Bcl2 in ovarian cancer." (PMID 24864239, 2014). "B-cell lymphoma 2 protein (Bcl-2) is currently under investigation as a reliable biomarker for ovarian cancer, and it has been shown that urinary Bcl-2 levels are reliably elevated during different stages of ovarian cancer." (PMID 23112714, 2012). "Based on the reliability of urinary levels of Bcl-2 as a biomarker for detecting ovarian cancer at early stages and distinguishing cancer from other gynecological conditions, the development of an ultrasonic biosensor has been undertaken to ultimately be used for point-of-care diagnosis." (PMID 23112714, 2012). "In conclusion, the results indicate that ChA21 could inhibit growth and induce apoptosis of human ovarian cancer cell line SK-OV-3 via regulating the balance between Bax and Bcl-2." (PMID 20214830, 2010). "While several studies have previously examined Bcl-2 or the contribution of tumor infiltrating lymphocytes separately for ovarian cancer prognosis, we sought to further determine the combined clinical relationship between Bcl-2 expression and lymphocyte filtration for ovarian cancer progression." (PMID 19852858, 2009). "In this pilot study, it appears that alterations in Bcl-2 expression and the number of lymphocytes may be to be correlated with ovarian cancer progression." (PMID 19852858, 2009). "We recently showed that resistance to E1A gene therapy in an ovarian cancer xenograft model could be overcome by downregulating Bcl-2 with a Bcl-2 antisense oligonucleotide." (PMID 17612393, 2007). "Furthermore, PEITC-mediated apoptosis induction was validated by increased activation of caspase-3, caspase-8, and caspase-9, and enhanced expression of Bax and c- PARP, while a significant reduction was noted in the expression of Bcl-2 in PEITC-exposed ovarian cancer cells." (PMID 37190316, 2023).
ovarian carcinoma (continued). "Therefore, regulation of BCL2 gene expression can induce apoptosis and decrease platinum medicine resistance in ovarian cancer cell line given the fact that apoptosis and autophagy are both highly conserved processes that preserve organizational and cellular identity, respectively." (PMID 37201030, 2023). "Our analysis of the expression levels of the BCL2 and cMYC genes showed a decrease in the transcript level (BCL2: 17.46% ± 3.26 vs. 100% ± 8.32; p < 0.05, cMYC: 37.56% ± 8.16 vs. 100% ± 9.12; p < 0.05) in the patients with ovarian cancer compared to the control group." (PMID 38003498, 2023). "Thus, DLGAP5 knockdown could attenuate cell growth and induce apoptosis via cyclin-dependent kinase 1/cyclin D1/Bcl-2 signaling in ovarian cancer cells." (PMID 36499051, 2022). "Our recent finding identified that BCL2A1, an inducible BCL2 member, not only protects cancer cells against cellular stress-mediated intrinsic (mitochondrial) apoptosis but also promotes tumor growth and metastatic progression in ovarian cancer peritoneal metastases." (PMID 35743298, 2022). "In ovarian cancer, the overexpression of HVEM (TNFRSF14), a member of the TNF receptor superfamily, is associated with the activation of AKT/mTOR signaling, promoting the expression of Bcl-2 and HIF-1α, which is positively associated with tumor proliferation and negatively related to cell apoptosis." (PMID 36358792, 2022). "Thus, targeting Bcl-2-mediated Ca2+ signal might be a potential approach to overcome drug resistance in ovarian cancer." (PMID 35851420, 2022). "In ovarian cancer cell line A2780 treated with this treatment, the percentage of apoptotic cells and nuclear condensation was increased in a concentration-dependent manner, and the expressions of caspase 8, caspase 3, caspase 9, and Bax were increased, while the expression of Bcl-2 was decreased." (PMID 36686745, 2022). "Likewise, AS treatment reduced Bcl-2 and enhanced Bax in human ovarian cancer cell line SKOV-3." (PMID 34031264, 2021). "Interestingly, in a recent study, the inhibition of BCL-2 using ABT737 in ovarian cancer cells resulted in lower glycolysis and PKM2 levels in a mechanism mediated by the Sirt3-HIF1α axis, suggesting a potential role of BCL-2 in regulating PKM2, a finding that requires further exploration." (PMID 33503959, 2021). "One such example of ovarian cancer study demonstrated that ivermectin was found to cause DNA damage through the induction of double-strand DNA breaks and induces intrinsic apoptosis by disrupting the mitochondrial membrane associated with the upregulation of BAX/BCL-2 and cytochrome C release." (PMID 34684095, 2021). "In addition, Bcl-2 downregulation in SK-OV-3 ovarian cancer cells increases Ca2+ levels in the cytosol and in the mitochondria, as well as the number of ER–mitochondrial contact points after cisplatin treatment, thereby increasing the sensitivity to the chemotherapeutic agent." (PMID 30884858, 2019). "Studies further showed that OST could inhibit cell proliferation and induce apoptosis through targeting PI3K/Akt and MAPK signaling pathways in rat glioma C6 cells and via regulating apoptotic proteins Bcl-2, Bax, and Caspase 3/9 in ovarian cancer A2780 and OV2008 cells." (PMID 31354479, 2019). "Besides, DDB2 participates in sensitizing ovarian cancer cells to cisplatin-mediated apoptosis through the downregulation of the bcl-2 (B-cell lymphoma 2) transcriptional machinery in a HDAC1-dependent (Histone deacetylase 1) manner and the ubiquitylation of the antiapoptotic protein bcl-2." (PMID 31635251, 2019). "Furthermore, the quantification of BCL2 mRNA levels in lymphocytes obtained from ovarian cancer patients from Sheba Medical Center displayed a sevenfold increase in expression levels in lymphocytes from patients who presented the BCL2 sequence with the 21 T > C form." (PMID 31044156, 2019).